IL6 (interleukin 6)
Diseases named in the same sentence as IL6 in open-access papers (continued):
Sharing a sentence is not in itself a finding about the gene and the disease.
COVID-19 (continued). "Eight miRNAs displayed altered expression in anterior nasal tissues from COVID-19 patients, with miR-142-3p, a negative regulator of interleukin-6 (IL-6) production, the most strongly upregulated." (PMID 35381016, 2022). "Correlations of NP with IL-6 in both COVID-19 and non-COVID-19 patients were also weaker (rs = 0.393, p = 0.00753 and rs = 0.444, p = 0.0338)." (PMID 35529699, 2022). "The recognition of HIF-1α and IL-6, as being important pathogenetic factors in COVID-19, gives renalase a potential, yet unrecognized, role in COVID-19." (PMID 36132227, 2022). "The ability of PBM to decrease IL-6 levels in patients is therefore strong evidence of the anti-inflammatory potential of this strategy in the fight against severe forms of COVID-19, and its importance in the therapeutic armamentarium." (PMID 35874678, 2022). "The most probable cause of IDO enzyme activation in COVID-19 is the increased level of pro-inflammatory cytokines including IFN-γ, IL-1β and IL-6 and activated oxidative stress pathways, which both potently stimulate IDO." (PMID 35840908, 2022). "After detraining due to COVID-19, the IL-6 in 20s’G increased by about 18%, 30s’G by 21%, 40s’G by 22%, 50s’G by 16%, and 60s’G by 47%." (PMID 35162870, 2022). "Among the cytokines, IL-6, whose level in the plasma of COVID-19 patients is very high, is particularly important for predicting the disease progression and severity." (PMID 36140425, 2022). "CRP and IL-6 levels were also increased in COVID-19 patients with AKI, suggesting that the inflammatory storm was stronger in COVID-19 patients with AKI than in those without AKI." (PMID 35656097, 2022). "The levels of IL-6 were significantly higher in COVID-19 patients than healthy individuals (7.63 ± 6.30 vs. 5.54 ± 2.10, P=0.006)." (PMID 36381078, 2022). "TXA2 and NF-κB p65 had AUC higher than 0.8 in moderate COVID-19 patients, and IL-6 had AUC higher than 0.8 with a sensitivity of 100% in severe COVID-19 patients." (PMID 36298501, 2022). "In a prospective study of immune-inflammatory biomarkers conducted on 153 COVID-19 patients, IL-6 was confirmed as the most accurate and highly predictive inflammatory biomarker of mortality." (PMID 36366457, 2022). "Similar laboratory results show progressive reduction of lymphocytes in COVID-19 patients; among the various cytokine changes, interleukin-6 (IL-6) and IL-8 were the most significant." (PMID 36341356, 2022). "Therapeutic agents targeting IL-6 have been applied to clinical practice, which improved the outcomes of severe and critical COVID-19 patients." (PMID 35540724, 2022). "Patients infected with COVID-19 harbour an expanded population of circulating monocytes that secrete IL-6 and IL-1β, as a result, patients with COVID-19 have elevated serum IL-6 as well as lactate dehydrogenase levels compared with healthy controls." (PMID 35843719, 2022). "High expressions of proinflammatory cytokines such as interferon-γ (IFN-γ), IFN-α, and IL-6 were observed in the serum of patients with COVID-19." (PMID 36052305, 2022). "This study also focused on the changes of immune system in COVID-19 patients with cancer, and compared IL-6, white blood cells and lymphocyte subsets." (PMID 36439504, 2022). "Our study also found a higher expression of IL-6 and IL-8 in patients with severe COVID-19 than in those with mild COVID-19." (PMID 35687545, 2022). "According to current literature, alveolar macrophages such as APCs can release IL-6, IL-23, and many other cytokines in COVID-19." (PMID 35619180, 2022). "Based on such premises, it seems very likely that these mechanisms are also fully operative in patients with severe COVID-19, where high-grade systemic inflammation and elevated IL-6 levels are characteristically present." (PMID 35665254, 2022). "Here, we analyzed the ROC of Interleukin 2 receptor, Interleukin 6, glucose, NT proBNP, and myoglobin for the diagnosis of severe COVID-19 in six age groups." (PMID 36233840, 2022).
COVID-19 (continued). "To determine how gene expression varies based on normalization with CypA and GAPDH, we looked at genes such as NRF2, IL-6, and IL-15, whose expression profiles based on RNA sequencing were previously reported in COVID-19 patients (30, –, 33)." (PMID 36377893, 2022). "In this study, we also found an increase in IFN-γ, TNF-α, IL-1 β, IL-6, and IL-10 in the V-COVID-19 group, which included patients that required hospitalization." (PMID 36497139, 2022). "Patients with severe COVID-19 exhibit increased secretion of IL-2R, IL-6, and TNF-α, and elevated circulating levels of IL-6 and TNF-α are independent predictors of mortality." (PMID 35929616, 2022). "A recent study shows that serum IL-6 levels can effectively assess the severity of COVID-19 and predict disease progression in patients." (PMID 35676519, 2022). "The aim of the present study was to analyze the impact of IL-6 and new-onset AF on mortality rate in hospitalized COVID-19 patients stratified for PaO2/FiO2." (PMID 35454369, 2022). "On the other hand, a significant increase in IL-6 level was observed in COVID-19 patients compared to patients with influenza." (PMID 35237386, 2022). "For instance, the mean IL-6 concentration value of COVID-19 mothers was 5 times higher than that of the vaccinated group, which in turn was five times higher than the control group." (PMID 36560410, 2022). "In a subset of COVID-19 patients with an altered blood-brain-barrier, increased levels of specific cytokines, such as IL-6, in the cerebrospinal fluid (CSF) were detected." (PMID 36713399, 2022). "Our study shows that the inflammatory marker IL-6 proves to be a better indicator of the outcome of COVID-19, with a sensitivity of 81.5% and specificity of 81.8% with a cut-off value of 37.5." (PMID 36381779, 2022). "Our results show that 8-isoprostanes and IL-6 were elevated in both moderate and severe COVID-19 patients." (PMID 35326383, 2022). "IP-10 and MCP-1, MIP-α, IL-6, and CC genotype of rs12252 (42 T/C) SNP of IFITM3 gene are associated with COVID-19 severity." (PMID 35822078, 2022). "The SNPs and plasma analyses (ABG, IL-6 and Vitamin D) of healthy (blue color) and COVID-19 groups (orange color) showed specific traits suggestive of either susceptibility or protective features." (PMID 36428884, 2022). "In contrast to moderate COVID-19 patients, severe COVID-19 patients had higher levels of IL-6, but IL-4, IL-18, and IL-35 between both illness categories were at close levels." (PMID 36675695, 2022). "SARS-CoV-2 appears to downregulate the expression of ACE-2 on peripheral blood monocytes which show an activated phenotype in COVID-19 evidenced by morphology and IL-6, IL-10, and TNF-α production." (PMID 35913134, 2022). "Our results are important because it was possible to identify differences in cytokine synthesis and identify characteristic profiles in acute COVID-19 (higher levels of IL-6) and long COVID-19 (high levels of IL-2 and IL- 17)." (PMID 35846757, 2022). "In line with this, systemic levels of enzymatically active ACE2 increased in severe COVID-19 patients compared to less severe cases, and correlated with systemic IL-6 levels." (PMID 35308535, 2022). "This viremia and virus replication results in serious symptoms, one of which is the triggering of cytokine storms, including interferon-alpha, IL-2, IL-6, IL-10, and C-reactive protein, which can erode the health of COVID-19 patients." (PMID 35812166, 2022). "The same is copied in many other studies, which concluded mounting levels of TNFα, IL-6, and IL-10 in severe COVID-19 patients in comparison to those with mild-to-moderate manifestations." (PMID 35203844, 2022). "One evidence is that corticosteroid therapy in COVID-19 patients targeting IL6 and other cytokines showed better outcome." (PMID 36369012, 2022).
COVID-19 (continued). "The effect of H2S on the level of IL-6, which is a major mediator of inflammation in COVID-19, was examined, as the level of this interleukin is a reliable indicator of disease severity and the patient’s chances of survival." (PMID 36140256, 2022). "Among others, IL-6 and TNF-α are over-expressed in COVID-19 while the IL-1 family is strongly associated with acute inflammation." (PMID 36037223, 2022). "Our data confirm and extend prior findings of Gal-3BP mediated IL-6 induction, enlightening the potential of its antibody-mediated s blockage for the prevention and treatment of CS and severe disease in COVID-19 patients." (PMID 36220879, 2022). "Mild COVID-19 patients had significantly high pGSN/IL-6 amongst all the multi-analyte markers following day 4 of symptoms onset compared with moderate and severe COVID-19 patients, and pGSN/IP-10 and pGSN/HGF showed a trend toward this association." (PMID 36148234, 2022). "Upon hospitalization, PDM patients exhibited higher serum levels of interleukin 6 (IL-6), which is related to reduced partial pressure of oxygen (PaO2) in arterial blood, oxygen saturation (SpO2) and increased COVID-19 severity." (PMID 35898449, 2022). "The inflammation of the olfactory epithelium in COVID-19 seems to be supported by the release of cytokines such as IL-1, IL-6, IL-12, IL-15, and TNF-α, and by activating lymphocytes and macrophages, initiating the so-called “cytokine storm”." (PMID 35269410, 2022). "We systematically searched records investigating the role of interleukins (IL-1β, IL-2, IL-4, IL-6, IL-8, and IL-10) in COVID-19 patients in Web of Science, Pubmed, and Embase through December 2020." (PMID 35540724, 2022). "Lastly, underweight patients with cirrhosis and COVID-19 were in the group with the highest risk factor for developing ACLF and ICU admission, where procalcitonin levels along with CRP, IL-6, and fibrinogen were all significant independent risk factors." (PMID 35160114, 2022). "Supernatants were subsequently analyzed for key inflammatory cytokines associated with the cytokine storm in COVID-19 (IFN-γ, IL-1β, IL-2, IL-4, IL-6, IL-8, IL-10, IL-12p70, IL-13, and TNF-α), using the Meso Scale platform." (PMID 36296272, 2022). "Both individual studies and systematic reviews indicate the importance of IL-6, reporting it to be an independent predictor of disease severity and survival in COVID-19 patients." (PMID 36248417, 2022). "Immunologic findings in patients with COVID-19 include elevated serum C-reactive protein and pro-inflammatory cytokines (e.g., IL-6) and decreased total blood lymphocyte counts." (PMID 35646985, 2022). "We found that 0.01% to 10% of the COVID-19 patient sera clearly enhanced the IL-6 production induced by N protein." (PMID 35577892, 2022). "For the first time, we demonstrated that in severe COVID-19, systemic inflammatory activation can per se promote QTc prolongation via IL-6 elevation, leading to ventricular electric remodeling." (PMID 35665254, 2022). "Elevated levels of CRP and interleukin-6 (IL-6) were observed in AF patients accompanying COVID-19, indicating increased inflammation." (PMID 35796916, 2022). "This meta-analysis aims to determine the relationship, if any, between TNF-α, IL-6, vitamin D, and COVID-19 severity and mortality." (PMID 35215138, 2022). "This is the reason why IL-6 inhibitors (tocilizumab, siltuximab and sarilumab) had been proposed as potential therapies in critical COVID-19 patients." (PMID 35584141, 2022). "Overall, these findings identify IL6 an important therapeutic target not only for COVID-19 symptoms in general, but also for those neurological manifestations which are commonly observed as a consequence of the disease." (PMID 36195636, 2022). "As one of the major cytokines regulating inflammatory response in COVID-19, serum interleukin-6 (IL-6) has been observed to correlate with mortality, and proposed as a biomarker predictive of disease severity." (PMID 35707401, 2022).
COVID-19 (continued). "AM3 supplementation improves COVID-19 outcomes by decreasing the systemic levels of IL-6, TNF-α, CRP and ferritin and the enzymes ALT, AST, LDH, CK, and MB." (PMID 36458163, 2022). "As a marker of the cytokine storm, serum levels of IL-6 and IL-8 were evaluated in the COVID-19 groups and HC at baseline and in the moderate and severe COVID-19 patients over 5–7 days of treatment with remdesivir and dexamethasone." (PMID 35187271, 2022). "IL-6 signalling was insufficiently inhibited in patients with COVID-19 or iMCD treated with standard doses of anti-IL-6 therapy." (PMID 35928820, 2022). "Of interest, 6 proteins (IL-6, CKAP4, Gal-9, IL-1ra, LILRB4, and PD-L1) were associated with the severity of COVID-19." (PMID 36403043, 2022). "SASP components include the proinflammatory cytokines IL-1β and IL-6, which are elevated in plasma of COVID-19 patients that have acute respiratory distress syndrome or systemic inflammatory features." (PMID 35086840, 2022). "Following recent findings, showing high circulating LRG1 levels in COVID-19 patients, we propose that IL-6 is driving LRG1 production in the lung resulting in some of the pulmonary vasculopathy observed." (PMID 35318338, 2022). "The following equation was obtained: Probability (severe/critical COVID-19) = 1/1 + exp − [− 2.458 + (0.065 × age) + 2.214 × diabetes mellitus + (− 0.004 × CD3+ T cell count) + (0.006 × IL–6)." (PMID 35346253, 2022). "ADAM17 has been implicated in modulation of COVID-19 pathogenesis through regulation of ACE2 shedding, IL-6 signaling, and TGF-β signaling." (PMID 36494335, 2022). "In the second step, hit compounds were studied in a wide range of concentrations as inhibitors of NO synthesis and IL-6 secretion, which is considered a key mediator of cytokine release syndrome and severe COVID-19." (PMID 35631365, 2022). "Key findings of this investigation were as follows: Levels of LDL-C, HDL, TC, and TG all decreased significantly with increasing severity of COVID-19 while acute phase reactants like IL-6, Procalcitonin, CRP, and D-dimers were increased in this cohort." (PMID 35637852, 2022). "For example, for IL-6 more than 50% of the healthy patients in Lima and Huaraz show levels below the first quartile (10 pg/ml), on the contrary, COVID-19 patients show greater percentage in upper values." (PMID 35090394, 2022). "IL-6 is one of the factors behind the cytokine storm that occurs in the most severe cases of COVID-19 and serum levels of this cytokine are therefore a widely recognized negative prognostic factor." (PMID 33983525, 2022). "Incubation with the TLR7/TLR8 agonist induces the production of TNF-α and IL-6 in cells from HDs and COVID-19 patients." (PMID 36248842, 2022). "Among cytokines, interleukin 6 (IL-6), TNF and IL-1β have been identified as key targets associated with PF secondary to COVID-19." (PMID 35308222, 2022). "IL6 expression is typically high during acute COVID-19, especially in severe disease, and induces hepcidin production." (PMID 35736479, 2022). "In this context, it seems likely that anti-IL-6 therapy can offer certain benefits in at least some patients with COVID-19 if properly indicated." (PMID 35867145, 2022). "In comparison to mild/moderate cases of COVID-19, plasma from patients with severe cases showed a greater tendency for levels of IL-6, IL-8 and TNF-α indicating a pro-inflammatory response." (PMID 35958594, 2022). "The ROC curve data further revealed that CRP, SAA and IL-6 levels had excellent sensitivity and specificity for COVID-19 severity." (PMID 35958594, 2022). "Due to the systemic inflammatory response observed in COVID-19 patients, the involvement of upregulated proinflammatory cytokines, especially IL-6 in hyperalgesia, a stated characteristic of myalgia, has been anticipated." (PMID 35624818, 2022). "Data for IL-6 and IL-1 inhibition in COVID-19 treatment have been largely positive, suggesting a mortality benefit." (PMID 36579506, 2022).
COVID-19 (continued). "Critically, patients with COVID-19 experienced pneumonia-like symptoms and substantially elevated blood IL-6 levels." (PMID 36111104, 2022). "The positive correlation between the P2X7 receptor and CRP increased in the moderate and severe COVID-19 groups, but in contrast, the positive IL-6 and IL-15 correlation with CRP decreased in these groups." (PMID 35663992, 2022). "In a recent article, Magro found that an IL6 of >40 pg/ml is indicative of cytokine storm in COVID-19 patients." (PMID 35836784, 2022). "Inhibits JAK3, JAK1, JAK2, and to a lesser extent TYK2 and inhibits receptor signaling through pairs of JAK2 and because it can suppress the production of different cytokines, such as IL-2, IL-7 and IL-6 can used for patients with COVID-19." (PMID 36111104, 2022). "Several inflammatory response markers including procalcitonin, serum ferritin, C-reactive protein (CRP), D-dimer, and interleukin-6 (IL-6), which have been found to correlate significantly with severity of disease and poorer outcomes of COVID-19 patients." (PMID 35160150, 2022). "Firstly, active NLRP3 inflammasome and caspase-1 are detected in the peripheral blood and tissues of COVID-19 patients and are positively correlated with severity markers for COVID-19 (e.g., IL-6)." (PMID 36532040, 2022). "High levels of proinflammatory cytokines, such as IL-1, IL-6, IL-7, IL-12, IFN-γ, TNF-α, IP-10, MIP-1A, MCP-1, GCSF, and IP-10, have been observed in COVID-19 patients and are generally associated with severe lung damage." (PMID 34463916, 2022). "There was persistent systemic inflammation after 28 days following COVID-19, including elevated concentrations of interleukin (IL)-6, tumour necrosis factor-α, and CCL-11." (PMID 35397798, 2022). "Meanwhile, higher numbers of CD4+ T-cell subtypes expressing GM-CSF and IL-6+ were observed in COVID-19 patients in the ICU with more severe pneumonia." (PMID 35615369, 2022). "Elevated levels of C-reactive protein, interleukin-1B, and interleukin-6 have become key signatures of severe COVID-19." (PMID 36431059, 2022). "Sera from COVID-19 patients also enhanced IL-6 production, and sera from patients with severer disease induced higher levels of IL-6." (PMID 35577892, 2022). "In the COVID-19 scenario with mAb concentrations at 1% of those in plasma, IL-6 bioactivity was minimally inhibited even with repeated daily injections of anti-IL-6 or anti-IL-6R mAb, either alone or in combination." (PMID 35928820, 2022). "IL-6 is a key mediator of inflammation in COVID-19, and its receptor antagonist (sarilumab/tocilizumab) and IL-6 inhibitors (clazakizumab/siltuximab/sirukumab) have been described as potential immunotherapeutics to manage SARS-CoV-2 viral infections." (PMID 36362351, 2022). "COVID-19-induced cytokine storms are effectively treated with this drug by decreasing the level of IL-6." (PMID 35261539, 2022). "Despite the encouraging evidence of anti-IL6 agents in COVID-19, some treatment failures have been reported." (PMID 35619180, 2022). "Our results demonstrate that melatonin consumption for 14 days significantly decreases plasma levels of IL-4, IL-2, IL-1β, IFN-γ, and IL-6 in COVID-19 patients." (PMID 36254292, 2022). "Of note, inflammatory cytokine milieu characterized in chronic HIV infection shares overlapping targets that are also identified in severe COVID-19, featuring increased level of interleukin-6 (IL-6), IL-10 and tumor necrosis factor (TNF)." (PMID 34843064, 2022). "As shown in previous studies, COVID-19 is characterized by the upregulation of pro-inflammatory cytokines which was evident in our study with the upregulation of IL-6, IP-10, M-CSF, HGF, CTAK and TGF-b1." (PMID 36148234, 2022). "The results show that MMP-7, TGF-β, IL-10, IL-7, TNF-α, and IL-6 were significantly correlated with high lung involvement in COVID-19 patients." (PMID 36286038, 2022).